TNF (tumor necrosis factor)
Diseases named in the same sentence as TNF in open-access papers (continued):
Sharing a sentence is not in itself a finding about the gene and the disease.
infection (continued). "We infected human (THP-1) or mice macrophages (MHS) at MOI 1:1 for 1 h with either the wild type H37Rv, the Δpmt mutant, and the Rv1002c-complemented strain and assayed inflammatory (TNF-α) or anti-inflammatory (IL-10) cytokines at 5, 24 and 48 h post-infection." (PMID 28801649, 2017). "Microglial cells could be rapidly activated in response to infection, inflammation, or brain injury, and thus lead to the releases of various inflammatory mediators, including IL-1β, IL-6, TNF-α, nitric oxide, reactive oxygen species, and prostaglandin E2." (PMID 28804270, 2017). "The same was also true for infection-induced TNF-α secretion of the DCs." (PMID 28634388, 2017). "Notably, while Ly6Chi monocytes are not productively infected by L. pneumophila, they produce important proinflammatory cytokines, including TNF, which is required for successful control of infection." (PMID 28384349, 2017). "Our findings in the present study are consistent with earlier observations that in healthy keratinocytes, IL-6 is only minimally expressed, but at sites of infection, IL-6 overexpression is stimulated by various other cytokines, including IL-1, TNF-α, and INF-γ." (PMID 29152103, 2017). "Furthermore, following infection with Streptococcus pneumoniae, increased TNF-α concentrations in the BAL and MC numbers in the lung correlated with protection." (PMID 29089945, 2017). "Furthermore, OPN did not appear to contribute to BBB compromise directly in our mouse model, while Opn−/− mice had reduced gene expression of Icam-1 and TNF-α levels early in the course of infection (D2 p.i.)." (PMID 28680095, 2017). "In the present cohort, TNFα-producing CD4 cells were also associated with protection from infection in univariate analysis, but this association was not significant after controlling for exposure intensity and age." (PMID 29097996, 2017). "However, suppression of TNF-α level at late stage of infection by both the antibiotics in presence of Riboflavin indicates the combination to be effective in down regulating inflammation with increasing time which was beneficial to the host cell." (PMID 27932936, 2016). "HBV is considered a non-cytopathic virus and it may utilise diverse mechanisms to abrogate TNF-mediated antiviral responses to infection." (PMID 27551508, 2016). "Despite the demonstration that Mabs R induces a stronger TLR2-mediated TNF response than Mabs S, there is little information regarding the events leading to the inflammatory response in Mabs infection and how the inflammation impacts on the outcome of the disease." (PMID 27806130, 2016). "One possible explanation is that impaired TNF-α production by MAIT cells may be due to anergy or exhaustion of these cells during infection." (PMID 27463223, 2016). "In addition, probiotic therapy successfully suppressed the infection-dependent induction of TNF-α and interleukins 6 and 10 in the liver." (PMID 27780258, 2016). "However, infected Mif−/− mice displayed reduced numbers of TipDCs (P = 0.0049) and TNF-α+ iNOS− CD11b+ (P = 0.0090) DCs at 5 days after infection." (PMID 27057101, 2016). "Interestingly, EPEC and EHEC infection induced low secretion of TNF-α at 0.5, 1, and 2 h post-infection with values around 0.0005 ng/ml." (PMID 27774437, 2016). "Clusters of pathogens appeared to group according to the hypersusceptibility status rather than the TNF-α/IL-10-fold change levels, suggesting that it is likely a risk factor for repeated infections in general, rather than to specific pathogens." (PMID 27761434, 2016). "This indicates that PCV2 may inhibit IL-6 and TNF-α signal transduction in PBMCs in subclinical infections." (PMID 27581515, 2016). "TNF-α is an important proinflammatory cytokine secreted by many cell types, such as macrophages, lymphocytes, fibroblasts, and keratocytes, in response to an inflammatory reaction, infection, or environmental changes." (PMID 28044068, 2016).
infection (continued). "BMDM infection with Escherichia coli also showed increased IL-1β production in Card9−/− in comparison with WT macrophages without affecting pyroptosis, intracellular bacteria counts and TNF-α production." (PMID 27670879, 2016). "Therefore, we decided to investigate if the enhancing role of TNFα in SVCV replication was the result of impairing the interferon response during SVCV infection." (PMID 27351838, 2016). "The early modification of interleukin-1 and TNF-α in the drainages may best predict surgical-site infection." (PMID 27938371, 2016). "Moreover, the antiviral activity can be amplified by the chemoattractant function of the chemokines which recruit leukocytes to the site of infection and activate these cells to secrete the proinflammatory cytokines (TNF-α, IL-1β and IL-6)." (PMID 27538960, 2016). "As for the right (non-infected) paws of mice infected with high dose L. major the effect of atenolol on the levels of TNF-α was only significant at day 4 post infection becoming 28.29 ± 15.27 pg/hind paw as compared to 79.01 ± 7.91 pg/hind paw for the infected atenolol untreated mice (p < 0.01)." (PMID 26913003, 2016). "During acute infection with L. interrogans serovar Icterohaemorrhagiae, hamsters upregulate gene expression of TNF-α, TGF-β, IP-10 (CXCL10), and IL-10 at the site of infection (kidney) and peripheral blood mononuclear cells upregulate expression of TNF-α, IFN-γ, IL-12." (PMID 27486445, 2016). "In the second line, the cAMP-mediated downregulation of pro-inflammatory IL-12 and TNF-α production and the upregulation of anti-inflammatory IL-10 cytokine release by myeloid cells, would skew the adaptive immune responses to infection and protract bacterial colonization." (PMID 27581058, 2016). "In addition, anti-TNF therapies to treat autoimmune diseases exacerbate the infection produced by virus such as herpes simplex virus (HSV), Epstein-Barr virus (EBV), cytomegalovirus (CMV) and human papillomavirus (HPV)." (PMID 27351838, 2016). "Anti-tumor necrosis factor (TNF)-α antibody is effective in some IBD patients, but may cause serious infection in some predispose patients." (PMID 27499766, 2016). "Interestingly, both IGF-I and TNF-α reacted in parallel to both stimuli, E2 treatment and infection." (PMID 26821056, 2016). "This case demonstrates how autoimmune reaction to anti-TNFα therapy can initially mimic infection." (PMID 27822400, 2016). "It is interesting to note how the levels of IL-10 (a typically anti-inflammatory molecule) are strongly affected by the different effector T cell chemokine thresholds for recruitment at the site of infection as compared to TNF, which is more of a pro-inflammatory molecule." (PMID 28989808, 2016). "A dual role for TNFα may be proposed which could act as both a protective and detrimental cytokine, depending on the stage of infection." (PMID 27007501, 2016). "TNF-α-dependent apoptosis during WT infection may be countered by Cflar-and Nfkb-dependent anti-apoptotic responses." (PMID 27634329, 2016). "Infection of WT macrophages with N. caninum induced a marked production of IL-6 and TNF-α, and this response was partially suppressed in macrophages lacking Nod2, whereas IL-10 levels were increased in culture supernatants of Nod2−/− BMDMs at the initial replicative cycle of the parasite (8 h)." (PMID 27377650, 2016). "The authors suggestedthat IFN-g and TNF-a production in individuals with asymptomatic infection could be enoughto control parasite growth and prevent tissue damage." (PMID 27759762, 2016). "EHEC caused p65 phosphorylation and the increase of the phosphorylated protein band was about 80%, compared with those induced by the positive control (TNF-α) at 0.5 h of infection; this percentage decreased to about 50% at 1 and 2 h of infection until disappearing at 4 h." (PMID 27774437, 2016).
infection (continued). "The clinical evaluations and laboratory parameters (haemoglobin [Hb], white blood count [WBC], IL-6, IL-1b, TNF-alpha) did not reveal systemic signs of infection or blood loss." (PMID 27125302, 2016). "By two weeks after infection, lungs of pDC-depleted mice showed diminished levels of regulatory cytokines (TGF-β and IL-10), associated with increased levels of inflammatory cytokines such as IFN-γ, TNF-α, IL-12 and IL-6." (PMID 27992577, 2016). "IL-12, TNF-α, and IL-1β are proinflammatory cytokines, which are essential for resistance against infection, but when produced at high levels they may contribute to immunopathology." (PMID 27549173, 2016). "DV3P12/08 infection triggered the release of large amounts of TNF-α, IL-6, and MCP-1." (PMID 26844767, 2016). "In contrast, M28 GAS elicited significant cytokine increases in TNF-α, IL-17A, IL-6, IL-1β, and IL-22, as early as 3 to 7 days post-infection in the estradiol pulse model, and a significant cellular infiltrate in the lumen was observed in colonized WT mice compared to non-infected or IL-17A−/− mice." (PMID 27241677, 2016). "Furthermore, during infection, Clock (−/−) mice produce fewer pro-inflammatory cytokines (TNFα, IFNβ, IL-6, IL-1β) than WT mice." (PMID 27242972, 2016). "Monocyte-derived TNF-α/iNOS-producing CD11b+ DCs (TipDCs) can be induced during parasitic or microbial infections, and they exert potent antimicrobial functions required to control the infection." (PMID 27057101, 2016). "All these suggest that in our model p38 MAPK could regulate TNF-α secretion in response to E. coli pathotypes infection." (PMID 27774437, 2016). "While the binding of LPS to toll-like receptor 4 rapidly activates NF-κB which in turn induces cytokine and chemokine expression, LPS is also known to stimulate the release of TNF-α, an acute phase protein that is rapidly elevated in response to injury or infection." (PMID 26860080, 2016). "Protected vaccinates had a lower frequency of ESAT-6:CFP10-specific Tcm cells coproducing IFN-γ and TNF-α, suggesting that the incitement of strong Tcm IFN-γ/TNF-α responses early upon infection is related to a higher bacterial burden and inability of the host to control mycobacterial growth." (PMID 27799930, 2016). "Aldwell and the coworkers, by contrast, observed enhanced expression of genes for the proinflammatory cytokines IL-1β, IL-6, and TNFα only after in vitro infection of bovine macrophages in bronchoalveolar fluid with pathogenic M. bovis, but not with attenuated BCG-mycobacteria." (PMID 27066505, 2016). "In addition, cytokines like IL-6, IL-1, and S100 or TNF activate MDSC at the infection site, where MDSC are noted for T-cell inhibition and defects in phagocytosis and, at least for G-MDSC, accelerated apoptosis." (PMID 27015566, 2016). "Additionally, the ability to produce cytokines IFNγ, TNFα, and IL-2 was unaffected in aPKC-deficient CD8+ T lymphocytes at 50 days post-infection." (PMID 26765121, 2016). "We detected IL-10 and TNF-α in mouse sera 10 h after Absettarov-strain infection." (PMID 28163697, 2016). "We propose in this report that there is a novel pathway for 2-APB to regulate pathogen-induced TNF-α production in macrophages and that an inhibitory mechanism against pathogen infection by 2-APB mitigates a cytokine storm during a severe inflammatory response." (PMID 27472555, 2016). "The HCV-infection was controlled by the upregulation of TNF-α, IL-28B and IL-29." (PMID 27044429, 2016). "We found that low-dose ND8008 therapy could significantly reduce the initial infection, especially 6–12 hours later in the host serum pro-inflammatory cytokine (IL-1, IL-6 and TNF-α) content." (PMID 26839286, 2016). "The increased levels of soluble TNFR1 present during experimental S. aureus ST239 infection may neutralize circulating TNF-α and impair the host inflammatory response." (PMID 27446000, 2016).
infection (continued). "Therefore, we calculated the average IL-10: TNF-α ratio for a healing response, a hyperinflammatory response, and organ dysfunction during infection in 10 simulation runs." (PMID 27556404, 2016). "This could explain why an anti-HMGB-1 agent and/or an anti-TNF-α treatment become less effective as the infection proceeds." (PMID 27556404, 2016). "IL-6 and TNF-α are primary pro-inflammatory cytokines that could exhibit an acute phase response to tissue injury, infection, or inflammation." (PMID 27701469, 2016). "We believe that augmentation of intrathymic production of inflammatory cytokines, such as IFN-γ, IL-17 and TNF-α may be related to the participation of effector T cells which home to the thymus to control infection." (PMID 27736987, 2016). "Transient TNF-α depletion in mice at the time of infection with C. neoformans resulted in a temporary decrease in interleukin-12 (IL-12) and gamma interferon (IFN-γ) production during the afferent phase, followed by recovery of their production during the efferent phase." (PMID 27406560, 2016). "Furthermore, cytokine levels from vaginal washes of M28 GAS infected Rag1−/− and WT mice demonstrated that the Rag1−/− mice produced greater quantities of IL-1β, IL-6, and TNFα at 14, 21, and 28 days post-infection compared to WT mice." (PMID 27241677, 2016). "The increased levels of soluble TNFR1 present during systematic HA-MRSA ST239 infection may neutralize circulating TNF-α and impair the host inflammatory response." (PMID 27446000, 2016). "However, at 48 h post-infection, the mean level of TNF-α was similar between H7N9-HU (289-fold) and H7N9-CK (307-fold) (P = 0.802)." (PMID 26975414, 2016). "Infection with C. albicans increased intracellular TNF-α levels in PBMO and CBMO." (PMID 27870876, 2016). "Herein, through the use of loss- and gain-of-function approaches coupled with fluorescent reporter zebrafish lines and high resolution imaging, we have dissected the TNF/IL8-mediated signaling pathway that contributes to immuno-protection against Mabs infection." (PMID 27806130, 2016). "However, determination of cellular factors associated with the cda1Δ2Δ3Δ strain that resulted in the controlled expression of TNF-α production during infection will provide more insight into the regulation of TNF-α during C. neoformans infection." (PMID 27165801, 2016). "The strong proinflammatory environment caused by P. yoelii 17XNL infection could explain the delay on lesions development in co-infected groups, given the fact that IFN-γ and TNF play an essential role in controlling Leishmania replication inside macrophages." (PMID 27446022, 2016). "In turbot, during infection with Enteromyxum scophthalmi, the increased number of the TNF-α+ cells leads to the infiltration of inflammatory cells in the intestine and is associated with the development of the lesions, epithelial shedding and intestinal barrier dysfunction." (PMID 27231948, 2016). "A comparison of the peak level of HMGB-1 to the peak level of TNF-α reveals that the peak level of HMGB-1 is higher and that the time required to reach maximum concentrations of TNF-α was less than the time required for HMGB-1 (average of 9 hrs versus 24 hrs post infection)." (PMID 27556404, 2016). "Previously we had reported that extended treatment of macrophages with genistein inhibited the immune response to infections by C. albicans, as we had observed decreased phagocytic activity and TNF-α release when macrophages were incubated for at least 24 h with genistein." (PMID 26828477, 2016). "Tissue injury and infection can stimulate the production of TNF-α in periphery." (PMID 27187381, 2016). "The levels of proinflammatory cytokines like TNF-α and interleukin (IL)-1β and Th2 cytokines like IL-10 and IL-4 were measured by reverse transcription qPCR (RT-qPCR) in the liver, lung and spleen of the infected mice at day 7 post-infection." (PMID 26902658, 2016).
infection (continued). "Parasitic or microbial infections with Trypanosoma brucei or Listeria monocytogenes, respectively, induce potent inflammatory immune responses that generate iNOS/TNF-α-producing CD11b+ DCs (TipDCs), which derive from inflammatory monocytes recruited in the site of infection." (PMID 27057101, 2016). "Interestingly, that study also demonstrated that while infection of macrophages with HCMV induced the upregulation of TNF-α mRNA, treatment with lipopolysaccharide (LPS) was required for induction of TNF-α protein expression." (PMID 27182601, 2016). "In order to examine whether NF-κB is involved in the leaky expression of Ad genes, including the E2 gene, HeLa cells were pre-treated with recombinant human TNF-α (hTNF-α), followed by infection with WT-Ad." (PMID 26814140, 2016). "We hypothesized that sustained p55TNFR expression may allow for continued or amplification of TNF signalling yielding improved control of infection." (PMID 27995986, 2016). "As observed in humans, we found a BCG-associated upregulation of both TNF-α and IL-12 transcripts in all mangabeys analyzed, regardless of infection status." (PMID 27505158, 2016). "To further assess the effects of persistent p55TNFR expression on p75TNFR levels and the cytokine productions during reactivation of latent M. tuberculosis infection, we compared the levels of TNF, p75TNFR, NO and IL-12p70 in the lungs of WT mice and p55∆NS mice at 90 and 300 days post-infection." (PMID 27995986, 2016). "This hypothesis is supported by the release of numerous cytokines including TNFα following infection with EBOV/VP35m, which could stimulate DC maturation by induction of pathways other than the IFN-I pathway." (PMID 27930745, 2016). "However, a murine model of infection showed that DENV-infected endothelial cells in different organs, including the brain, were associated with bleeding, increased TNF-α production and endothelial barrier dysfunction." (PMID 27336851, 2016). "In the initial phases, infection with the AA43 and AA44 CF-adapted variants yielded lower recruitment of innate immune cells, including neutrophil and macrophage, and less MIP-2, KC, MIP-1α, IL-6, MCP-1 and TNF-α cytokines/chemokines production than AA2." (PMID 26883959, 2016). "Among the tested cytokines, the elevation of TNFα transcription in zebrafish infected by WT was 3.5 fold relative to the levels seen in uninfected fish, which indicates a strong inflammatory response of the host post infection." (PMID 27233038, 2016). "TNF-α stimulates endothelial activation and recruitment of leukocytes to the site of infection." (PMID 27733800, 2016). "Taken on its own, that observation is not incompatible with a higher non-specific proinflammatory (e.g. TNF) response being associated with future infection, as was observed here." (PMID 27653505, 2016). "Strikingly, five days post-infection, we found a significant defect in the percentage of TNF and IL-6 positive Ripk3-/-Casp8-/- inflammatory monocytes isolated from the mesenteric lymph nodes (mLN) of mixed BM chimeras compared with either wild-type or Ripk3-/- cells from the same animal." (PMID 27737018, 2016). "At the site of infection, TNF-α promotes activation of cells and recruitment of leukocytes." (PMID 27733800, 2016). "A Rifampicin plus isoniazid antibiotic treatment given on day14–35 post infection effectively reduced lung bacterial load by4 log10 in wild-type mice and allowed the survival ofsusceptible TNF and TNFR1-deficient mice from 4–5 weeks to11–12 weeks post infection." (PMID 26931771, 2016). "Since MCs and serglycin proteoglycans may contribute to the pro-inflammatory cytokine signaling during infection, we analyzed the serum levels of the pro-inflammatory cytokines TNF-α and IL-1β, and the regulatory cytokine IL-10." (PMID 27267469, 2016).